MED12 (mediator complex subunit 12)
Diseases named in the same sentence as MED12 in open-access papers (continued):
Sharing a sentence is not in itself a finding about the gene and the disease.
Uterine leiomyoma (continued). "In contrast another recent study has shown that MED12 alterations are equally distributed among karyotypically normal LM (69%) and uterine leiomyomas with some rearrangements (63%)." (PMID 22768200, 2012). "Until recently, MED12 and HMGA2 were thought to be mutually exclusive genetic events since no uterine leiomyomas had been found to harbor both alterations." (PMID 31027501, 2019).
Fibroadenoma (30 papers, 2015 to 2026). A benign tumor of the breast characterized by the presence of stromal and epithelial elements. "Of the four main subtypes of breast fibroadenomas, the MED12 mutation is closely correlated with intracanalicular fibroadenomas." (PMID 40385736, 2025). "For instance, mutations in the MED12 gene have been found to be prevalent in fibroadenomas, highlighting as intended genetic basis underlying these common benign lesions." (PMID 40703552, 2025). "This study aims to evaluate the prevalence and the prognostic role of fibroadenoma-like areas and MED12 mutations in patients with resected primary B-MPT." (PMID 39921370, 2025). "Research has shown that specific genetic mutations, such as those in the MED12 gene, occur frequently in benign breast tumors like fibroadenomas, suggesting a common genetic pathway in their formation." (PMID 40703552, 2025). "Recent studies on the molecular pathogenesis of PTs indicate that there are frequent Mediator Complex Subunit 12 (MED12) somatic mutations in both fibroadenomas and PTs, providing evidence that they share a common origin." (PMID 40919398, 2025). "This fact, together with the correlation between MED12 mutations and intracanalicular type fibroadenomas, suggests that MED12 is more closely related to the proliferation of fibrous components than that of epithelial components." (PMID 40385736, 2025). "Recent studies in the molecular pathogenesis of PTs show that Mediator Complex Subunit 12 (MED12) somatic mutation is often recognized in both fibroadenomas and PTs, thus proving that they both have a common origin." (PMID 38993445, 2024). "Genetic alterations, including MED12: Emerging research has identified specific genetic alterations, such as mutations in the MED12 gene, associated with some fibroadenomas." (PMID 38179396, 2023). "The results showed that organoids generally retained the genomic structure of the human fibroadenoma (MED12, APC genomic mutations) as patient samples." (PMID 37328469, 2023). "The MED12 gene mutations, in particular, have been observed in a subset of fibroadenomas, contributing to our knowledge of their genetic basis." (PMID 38179396, 2023). "Highly recurrent somatic mutations in the MED12 gene are reported in as many as 60–73% of breast fibroadenoma from Singapore." (PMID 35071776, 2022). "MED12 mutations occur in only a few tumor types, including LM and fibroadenoma of the breast implicating selective mechanisms that are tissue-specific." (PMID 35869560, 2022). "In mammals, MED12 is one of the most frequently mutated genes in breast fibroadenoma and is located on chromosome Xq13.1." (PMID 35071776, 2022). "Breast fibroadenoma (FA) and phyllodes tumour (PT) often have variations of gene mediator complex subunit 12 (MED12) and mutations in the telomerase reverse transcriptase promoter region (TERTp)." (PMID 33046803, 2021). "Breast fibroepithelial lesions are underpinned by recurrent MED12 exon 2 somatic mutations in stromal cells (59–67% of fibroadenomas and 45–67% of PTs), particularly in fibroadenomas and benign PTs." (PMID 33917271, 2021). "Although PTs account for a far lesser proportion of breast fibroepithelial lesions compared to fibroadenomas, both lesions share histomorphological features, as well as genetic alterations such as recurrent MED12 mutations." (PMID 32857809, 2020). "Breast fibroepithelial lesions (fibroadenomas and phyllodes tumors) are underpinned by recurrent MED12 exon 2 mutations, which are more common in fibroadenomas and benign phyllodes tumors." (PMID 29043292, 2017). "Exome sequencing has recently identified highly recurrent MED12 somatic mutations in fibroadenomas (FAs) and phyllodes tumors (PTs)." (PMID 27806318, 2016). "Here, we examined the MED12 mutation in phyllodes tumors, another biphasic tumor with epithelial and stromal components related to breast fibroadenomas." (PMID 25865354, 2015).
Fibroadenoma (continued). "Mutations in MED12 exon 2 were analyzed in nine fibroadenomas and eleven phyllodes tumors via Sanger sequencing." (PMID 25865354, 2015). "Similar to fibroadenomas, MED12 is the most frequently mutated gene in phyllodes tumour." (PMID 41611646, 2026). "Conversely, mastopathic-type fibroadenomas have less correlation with MED12 mutations and a low tendency for the proliferation of fibrous components, possibly allowing them to have ruffled borders and fat cell clusters near the tumor margins encompassed by peri-tumoral fat." (PMID 40385736, 2025). "The MED12 mutation is observed in more than half of breast fibroadenomas." (PMID 40385736, 2025). "MED12 mutations have been identified in the stromal component of fibroadenomas." (PMID 39105035, 2024). "However, the prognostic role of fibroadenoma-like areas and MED12 mutations in the context of primary B-MPT (ie, excluding patients with borderline and/or benign phyllodes tumors) is still unknown." (PMID 39921370, 2025). "MED12 mutations were found only in a few mesenchymal tumors, including LM and fibroadenoma of the breast, suggesting the selective mechanisms of MED12 in tumorigenesis of certain cell types." (PMID 39273004, 2024). "All three fibroadenomas (FAs) presented mutations in MED12, but not in TERT, whose mutation was observed in five of the 14 PTs." (PMID 38055384, 2023). "In a recent study, exome sequencing of 22 PTs and targeted sequencing of 100 fibroepithelial neoplasms revealed the genetic profile of fibroepithelial neoplasms, with MED12 (73%) and RARA (32%) mutations common in fibroadenoma patients and in all pathologically classified PTs' patients." (PMID 37771427, 2023). "Indeed, after restricting the observation only to patients with B-MPT, the association between MED12 mutations and fibroadenoma-like areas becomes non-significant (1/2 vs 1/9; exact Fisher’s test; P = .32)." (PMID 39921370, 2025). "In addition, further changes of chromosomes 1, 5, and 6 were noted but there were no mutations of MED12 as those frequently seen in fibroadenomas or phyllodes tumors." (PMID 33292379, 2020). "They found that PTs with fibroadenoma-like areas were more likely to harbor mutations in exon 2 of MED12, a gene often altered in benign breast fibroepithelial tumors, whereas PTs without fibroadenoma-like areas more commonly had mutations in EGFR and other known cancer genes." (PMID 29043292, 2017).
prostate carcinoma (22 papers, 2015 to 2025). A carcinoma that arises from epithelial cells of the prostate gland. "Taken together, all tested prostate cancer cell lines were susceptible to MED12 knockdown in both 2D and 3D settings." (PMID 39253786, 2024). "Dysregulated GLI3-dependent SHH signaling, as a result of mutant or downregulated MED12, has been shown to play an important role in X-linked disability syndromes and prostate cancer progression." (PMID 38915457, 2024). "Ultimately, these findings provide critical insight into the mechanisms underlying CRPC development for MED12-mutant prostate cancer." (PMID 37520466, 2023). "In this study, we have highlighted the role of the Mediator subunit 12 (MED12) in this process as MED12 is frequently mutated in prostate cancer and has previously been linked to regulation of SHH signaling." (PMID 37520466, 2023). "MED12 has been known to be frequently mutated in benign tumors, such as ULMs, phyllode, and prostate cancer." (PMID 35071776, 2022). "In prostate cancer cells, it was reported that the MED12 loss of function mutation promoted the androgen-independent cell growth of prostate cancer cells." (PMID 34572373, 2021). "In a more recent study, GLI3-FL was suggested to be involved in the induction of castration-resistant prostate cancer (GRPC) through a mutated form of MED12 which is common in prostate cancer." (PMID 32245491, 2020). "While in prostatic carcinoma, MED12 mutation sites were identified in exon 26 in the epithelial cells which seem to influence androgen signaling pathway." (PMID 31072327, 2019). "Additionally, mutations of MED12 in castration-resistant prostate cancer facilitate cell proliferation via the Hedgehog signaling pathway." (PMID 40888963, 2025). "Interestingly, the prevalence of MED12 mutations varies considerably among different prostate cancer study cohorts." (PMID 38379333, 2024). "This suggests that the direct inhibition of CDK8/19 may affect prostate cancer cells similarly to what was observed with MED12 loss." (PMID 39253786, 2024). "Moreover, there are conflicting views regarding the functional consequences of MED12 mutations in prostate cancer." (PMID 38379333, 2024). "Interestingly, prostate cancer-associated MED12 mutations lie within close proximity to XLID-linked mutations thus indicating that MED12 mutant prostate cancer likely involves a similar mechanism." (PMID 37520466, 2023). "Both SCLC and prostate cancer were reported to harbor MED12 mutations." (PMID 28055980, 2017). "Thus, we hypothesized that MED12 knockdown affects prostate cancer cell lines mainly through the subsequent loss of the kinase module activity." (PMID 39253786, 2024). "Since a common therapy for prostate cancer is androgen depletion, and in the presence of mutated MED12 SHH induced GLI3 gene expression is activated when androgen is absent, new or additional therapeutic approaches might be necessary to reduce the risk of prostate cancer relapse." (PMID 32245491, 2020). "MED12 knockdown induces apoptosis of prostate cancer cells and significantly inhibits the proliferation." (PMID 40940746, 2025). "Although our study is the first to relate MED12 to c-Myc in prostate cancer, MED12 depletion was already related to c-Myc expression in colon cancer." (PMID 39253786, 2024). "Based on these findings, we investigated the role of MED12 in prostate cancer cell models resembling various cancer stages and MED12 expression levels." (PMID 39253786, 2024). "Recent findings have shown that MED12 downregulation increased the proliferation of prostate cancer cells under androgen deprivation." (PMID 39253786, 2024). "Subsequently, we analyzed MED12 protein expression in a panel of prostate cancer cell lines (AR-positive: LNCaP, 22Rv1, VCaP, and DuCaP; AR-negative: DU145 and PC3) and in 1 benign prostatic hyperplasia cell line (BPH1)." (PMID 39253786, 2024).
prostate carcinoma (continued). "Consistent with the copy number data, we observed that 3 out of the 6 prostate cancer cell lines showed a strong increase in MED12 protein expression (>2× compared to benign BPH1 cells)." (PMID 39253786, 2024). "In this study, we have investigated this mechanism in a subset of prostate cancer that harbors genetic alterations within the Mediator subunit 12 (MED12)." (PMID 37520466, 2023). "Our findings have uncovered a novel role of MED12 in the progression of primary prostate cancer towards CRPC." (PMID 37520466, 2023). "In addition, MED12 knockdown in prostate cancer cells inhibited expression of c-MYC and its downstream proliferation-related genes and reduced the AR-driven tumor growth." (PMID 40940746, 2025). "To investigate the role of MED12 in prostate cancer, we analyzed aberrations in the MED12 gene copy number status in 2 publicly available datasets: treatment-naïve (TCGA-PRAD, primary prostate cancer) and CRPC (SU2C-PRAD, predominantly metastatic prostate cancer) tissues." (PMID 39253786, 2024). "In addition, 2 independent datasets from CRISPR- and RNAi-based screens (DepMap portal) revealed that nearly all prostate cancer cell lines were highly sensitive to MED12 downregulation, suggesting its pivotal role in prostate cancer cell growth and survival." (PMID 39253786, 2024). "MED12 protein expression was highly variable among the different prostate cancer cell lines." (PMID 39253786, 2024). "Thus, we simulated the prostate cancer MED12 mutant setting by generating a lentivirus mediated stable MED12 knockdown LNCaP cell line." (PMID 37520466, 2023). "Proliferation assays were performed on the MED12 knockdown cells to determine whether depletion of MED12 promotes hyperproliferation of prostate cancer cells." (PMID 37520466, 2023). "Therefore, in this study, we have investigated the link between MED12 and GLI3-dependent SHH signaling and how MED12 mutations promote progression of primary prostate cancer towards CRPC." (PMID 37520466, 2023). "Additionally, over-expression of MED12 in prostatic carcinoma as well as breast cancer has been observed." (PMID 31072327, 2019). "Since prior results have shown a link between loss of MED12 and hyperactivation of GLI3-mediated SHH signaling in prostate cancer and X-linked intellectual disability syndromes, we performed quantitative PCR to determine whether dysregulated signaling also occurs in breast cancer cells." (PMID 38915457, 2024). "Furthermore, the question remains whether there is a direct interaction between GLI3 and MED12 in prostate cancer." (PMID 32245491, 2020). "The MED12 copy number was increased in over 30% of CRPC samples, compared to less than 3% of treatment-naïve prostate cancer samples." (PMID 39253786, 2024). "MED12 mRNA expression was positively correlated with CDK8 and CDK19 gene expression in multiple primary prostate cancer tissue datasets, as expected by their common presence in the kinase module." (PMID 39253786, 2024). "We showed that MED12 and CDK8/19 inhibition downregulate the AR response and that they both affect prostate cancer cell response to enzalutamide." (PMID 39253786, 2024). "In conclusion, our study highlights the involvement of MED12 and CDK8/19 in c-Myc, AR activity, and cell response to enzalutamide in prostate cancer." (PMID 39253786, 2024). "Our study investigated how the inhibition of MED12 and CDK8/19 subunits affects cancer signaling pathways and cell processes in prostate cancer, focusing on AR activity and cell responsiveness to enzalutamide." (PMID 39253786, 2024).
prostate carcinoma (continued). "Despite providing novel insights into the role MED12 and CDK8/19 in prostate cancer, our study has several limitations." (PMID 39253786, 2024). "Clarifying the roles of MED12 and CDK8/19 in modulating AR and AR-Vs is crucial for understanding their impact on prostate cancer." (PMID 39253786, 2024). "In this study, we investigated how MED12 and CDK8/19 influence cancer-driven processes in prostate cancer cell lines, focusing on AR activity and the enzalutamide response." (PMID 39253786, 2024). "Taken together, these results suggest that MED12 and CDK8/19 play important roles in promoting tumorigenesis and resistance to therapy in prostate cancer cells." (PMID 39253786, 2024). "Our study revealed that MED12 and CDK8/19 regulate AR activity and that their inhibition may modulate response to enzalutamide in prostate cancer." (PMID 39253786, 2024). "Therefore, we conclude that MED12 expression is a key player in regulating prostate cancer cell growth specifically in the absence of androgens." (PMID 37520466, 2023). "Interestingly, we show that reduced MED12 expression does not significantly affect prostate cancer cell growth in androgen replete conditions, whereas we observed a significant increase in cell proliferation in androgen deprived conditions." (PMID 37520466, 2023).
leiomyosarcoma (18 papers, 2012 to 2025). An uncommon, aggressive malignant smooth muscle neoplasm, usually occurring in post-menopausal women. "Taken together, screening of 1158 samples representing various tumour types revealed five MED12 exon 2 mutations; three in uterine leiomyosarcomas and two in CRC samples." (PMID 23132392, 2012). "Five MED12 exon 2 mutations were identified in 1158 tumour samples, three in uterine leiomyosarcomas (3/41; 7%) and two in colorectal tumours (2/392; 0.5%)." (PMID 23132392, 2012). "Furthermore, mutations in MED12 have been identified in rare fibroid variations, including atypical, cellular, and lipoleiomyomas in addition to leiomyosarcomas and smooth muscle tumors with uncertain malignant potential." (PMID 39910492, 2025). "MED12 mutations were analyzed in the 12 uterine leiomyosarcoma samples." (PMID 27498619, 2016). "In our study we observed two uterine leiomyosarcomas exhibiting a MED12 mutation." (PMID 22768200, 2012). "Although most ULMS do not share common genetic drivers with ULs, MED12 hotspot mutations, HMGA2 overexpression and FH inactivation have been shown to occur in some ULMS cases, suggesting that leiomyosarcomas may originate from Uls." (PMID 40016412, 2025). "Furthermore, the literature holds several examples of leiomyosarcomas and STUMP (smooth muscle tumors of uncertain malignant potential) carrying MED12 mutations indistinguishable from those found in “ordinary” UL." (PMID 26468330, 2015).